IL6 (interleukin 6)
Diseases named in the same sentence as IL6 in open-access papers (continued):
Sharing a sentence is not in itself a finding about the gene and the disease.
infection (continued). "To investigate whether RBMX2 mediates intracellular inflammation by regulating the tightness of the epithelial barrier, we measured the mRNA levels of inflammatory factors (IL-1β, TNF, and IL-6) in RBMX2 knockout EBL cells post-infection." (PMID 41277807, 2025). "IL-6 is one of the primary mediators of cytokine storm, which is released during infection." (PMID 40438117, 2025). "The observed hematological alterations in LDM-2 rats suggest a heightened immune response and potential alterations in erythropoiesis due to infection or inflammation-related metabolic shifts, as inflammatory cytokines such as IL-6 and IFN-γ can suppress erythropoiesis during infection." (PMID 40357039, 2025). "Our experimental findings are consistent with these results, providing evidence of the destructive effect of a 6 h challenge with E. coli and Shigella, and showing that these infections significantly increased IL-6 and IL-8 production in IPEC-J2 cells to a great extent." (PMID 40426498, 2025). "We hypothesized that interleukin-6 (IL-6) is an early predictor of infection after pulmonary cancer surgery." (PMID 40549692, 2025). "Tumor necrosis factor-α (TNF-α) is a pivotal early mediator that recruits inflammatory cells to sites of infection; it activates neutrophils and lymphocytes, modulates tissue metabolism, and stimulates the release of other cytokines (e.g., IL-6 and IL-1β), acting synergistically in pain signaling." (PMID 41354715, 2025). "We have previously shown that infection with SARS-CoV-2 P21 causes increased production of a range of pro-inflammatory cytokines in the lungs of infected WT animals at multiple time points post-infection, including IL-1β, IL-18, IL-6, TNF, IFN-γ and others." (PMID 40016339, 2025). "However, there were no significant changes in expression levels of the pro‐inflammatory cytokines, IL‐6 and IL‐1β, in either muscle following infection." (PMID 39871399, 2025). "Interleukin-6 (IL-6) has important implications for immune response; it can serve as both an inflammatory cytokine in response to immune threats and exert anti-inflammatory effects after the injury or infection is resolved." (PMID 39860337, 2025). "Similarly, 24 h after infection, plasma IL-6 levels of infected vehicle were higher than sham controls." (PMID 40068933, 2025). "Specifically, RA significantly reduced IL-6 expression at later stages of infection, suggesting that it could mitigate virus-induced pro-inflammatory damage." (PMID 40732670, 2025). "Theoretically, selective inhibition of IL-6 trans-signaling could be expected to have a low impact on infection control and intestinal healing." (PMID 39857830, 2025). "During this period, the immune system is highly active, with massive proliferation of inflammatory cells (mainly granulocytes) and release of large amounts of inflammatory factors such as tumor necrosis factor-alpha and interleukins (IL-1, IL-6) to fight infection and injury." (PMID 40771209, 2025). "Notably, proinflammatory cytokine IL-6 gradually decreased among all infections until 14 dpi, in which JBNU-22-N01 showed a significant decrease compared with the negative control group at 14 dpi (P < 0.001)." (PMID 40459260, 2025). "When bacterial invasion activates intracellular NF-κB/MAPK signaling pathways, CDK9 is rapidly recruited to the promoter regions of immune genes, initiating the transcription of TNF-α, IL-6, and IL-1β genes and guiding immune cell migration to the infection site." (PMID 41515060, 2025). "The potential of cytokine IL-6 lies in its ability to act as early warning signals of infection." (PMID 40150583, 2025). "For infection severity diagnosis, ROC curve analysis demonstrated that serum TNF-α, IL-6, and IFN-γ levels had diagnostic value in assessing DFI infection severity, with AUC values of 0.811(95%CI: 0.734-0.927), 0.793(95%CI: 0.705-0.857), and 0.764(95%CI: 0.699-0.839), respectively." (PMID 40677522, 2025).
infection (continued). "When we considered the infection variable as a dichotomous variable (infection present/ absent) and applied the Mann-Whitney test, we obtained extremely significant differences in the IL-6 and CRP values." (PMID 40242671, 2025). "Increased levels of IL‐6 and IL‐8 were also observed in the supernatants after infection with STm." (PMID 39807570, 2025). "At the higher inoculum, WT and tlr4 mutant mice exhibited significantly increased levels of IL-1α, IFN-γ, TNF-α, MCP-1, IL-1β, IL-6, and IL-17A early during infection relative to the lower inoculum while levels dissipated by 7 dpi, consistent with bacterial clearance." (PMID 40817088, 2025). "Although early symptoms are often insidious, as the infection progresses, certain blood indicators, such as IL-6, ESR, and CRP, may rise, while WBC and PCT levels generally remain within normal limits." (PMID 40917673, 2025). "IL-6, however, is a proinflammatory cytokine produced after infection or injury." (PMID 40068933, 2025). "The rapid production of IL-6 contributes to host defense during infection." (PMID 40046856, 2025). "We also saw modest protein level increases upon infection for IFNα and IL-6 for both mouse strains." (PMID 39745442, 2025). "Interestingly, probiotic CFSs and vitamin D significantly reduced IL-6 production and cell cytotoxicity upon infection with the three periodontopathogens." (PMID 40351306, 2025). "Upon infection, VAN and DAP dampened expression of M1-associated genes (Tnf and Il6)." (PMID 41025812, 2025). "This phenomenon may be attributed to the prolonged exposure time to H2O2, given that IL-6 and IL-8 typically function during the initial stages of cellular infection or injury." (PMID 40298808, 2025). "RT-qPCR analysis at 12 hours post-infection indicated that NVP treatment strongly suppressed virus-induced transcription of pro-inflammatory cytokines Il6, Tnfα, and Il1β compared to the DMSO controls, approaching baseline expression levels in RAW264.7 cells across all viral challenges." (PMID 40948770, 2025). "IL-6 did not correlate with severe infection risk (p = 0.11 for microbiologically vs. clinically proven infections) or treatment outcomes in multivariate analysis." (PMID 40647525, 2025). "Likewise, MIP-2 and IL-6 assist in the recruitment of immune cells to the infection site, thereby modulating immune and inflammatory responses." (PMID 40589869, 2025). "MRS-produced LC04 CFS at 20% slightly counteracted infection-induced inflammation but still significantly increased IL-6 levels compared to the infection control (p < 0.0001), while vitamin D significantly reduced this effect (p < 0.0001), bringing IL-6 levels to those seen during infection." (PMID 40351306, 2025). "Three studies found IL-6 to significantly predict infection." (PMID 40004859, 2025). "During infection, proinflammatory Ly6Chi monocytes are recruited into the site of inflammation, where they differentiate into inflammatory macrophages that produce high levels of inflammatory cytokines such as IL-6, TNF-α, IL-1β." (PMID 38646937, 2024). "Currently, there have been no reports of IL-6 as a diagnostic indicator of infections after GC surgery." (PMID 38504206, 2024). "Therefore, we assessed the mRNA expression levels of the key inflammatory cytokines TNF, IL-6, and IL-1β following 6 h post-infection with S. anginosus or S. mitis by qPCR and supernatant protein levels following 24 h of infection by ELISA." (PMID 38289109, 2024). "Thirteen of the tested proteins (G-CSF, GM-CSF, M-CSF, TNF-β, IFN-gamma, TNF-α, IL-1 β, IL-3, IL-6, IL-7, IL-15, IL-17, IL-19) were found in the hemolymph and hemocytes of G. mellonella; however, the results regarding the influence of infection differed according to the detection method." (PMID 38774871, 2024). "This is the first report on the differences in responses of IL-4 and IL-6 to concomitant infection." (PMID 39195804, 2024).
infection (continued). "In addition to 6 dpi, the mRNA expression level of IL-6 was significantly different from PBS only in the PRE group within the time of infection." (PMID 40303164, 2024). "Notably, the concentrations of inflammatory cytokines TNF-α, IL-1β, and IL-6 were diminished in the serum and lungs of the LysoPE-treated mice on day five post-infection." (PMID 39390593, 2024). "However, as the infection progresses (7-dpi), IL-6−/− mice have higher fungal load in circulation and brain, suggesting the importance of this cytokine in Cn systemic dissemination and CNS colonization." (PMID 39334365, 2024). "To determine the mRNA expression levels of IFN-γ, TNF-α, IL-1β, and IL-18, as well as the abundance of cytokines IFN-γ, TNF-α, IL-6, and IL-10 in the kidneys of uninfected and PbA-infected mice at day 7 post-infection, we performed quantitative real-time PCR and CBA assays, respectively." (PMID 38787228, 2024). "Infection with live wild-type S. aureus induced the release of IL-6 and IL-1β." (PMID 38112465, 2024). "Similarly, IL-6 can regulate the growth and differentiation of a variety of cells and the immune response and plays an important role in the body’s anti-infection immune response." (PMID 39845801, 2024). "In our previous study, these parameters were 0.737, 67.5%, and 76.5%, respectively, for amniotic miR-4535; 0.649, 82.5%, and 52.9%, respectively, for amniotic 16S rDNA; and 0.664, 57.5%, and 76.5%, respectively, for amniotic IL-6 to predict fetal morbidity due to infection." (PMID 39574982, 2024). "High levels of basal IL-6 (at the time of infection) may contribute to host defense in female mice through the stimulation of acute phase responses." (PMID 38999932, 2024). "In this study, we identified several proteins (FABP4, LEP, RARRES2, MSTN, C2, SELE and IL6) that belong to a family of chronic pro-inflammatory cytokines and are primarily produced in response to infection or stress, some of which are mainly produced by adipose tissue (FABP4, LEP and RARRES2)." (PMID 38548792, 2024). "It is interesting that despite high infection levels of periodontopathic bacteria, the only inflammatory cytokines expressed in gingival tissue were IL-6 and CXCL2, which may reflect the “stealth” like properties of P. gingivalis as a keystone pathogens." (PMID 38233485, 2024). "Further studies will need to clarify whether the protective role against a severe disease course of higher baseline pre-infection levels of IL-6 extends to other infectious diseases." (PMID 39062668, 2024). "IL-6 with an optimal cutoff value of 84.00 pg/mL (AUC 0.84), PCT with an optimal cutoff value of 1.39 ng/mL (AUC 0.80), CRP with an optimal cutoff value of 150.00 mg/L (AUC 0.76) on POD 3 had superior diagnostic accuracy in predicting postoperative infections." (PMID 38504206, 2024). "Following infection with M. tb, NF-κB is activated and translocates to the nucleus, where it stimulates the expression of a range of proinflammatory cytokines, such as IL-1β, IL-6, and TNF-α." (PMID 38920649, 2024). "Meanwhile, TNFα or IL-6 levels decreased in 10aa−/− mice post-infection." (PMID 39519103, 2024). "At day one post-infection, there were increases in human IL-6, IFN-γ, MCP-,1, and MIP-1β." (PMID 39061322, 2024). "The expression levels of interleukin 1 beta (IL-1β), IL-6, IL-8, IL-10, IL-17A, and the interleukin receptor IL-17RA were significantly increased after infection with Yb2 and cYb2ΔsspA and were much greater than those in the brains of control and Yb2ΔsspA-infected ducks at 24 and 48 hpi." (PMID 38594770, 2024). "KC/GRO acts as a chemoattractant for neutrophils and other phagocytes, playing a role in the acute inflammatory response, whereas IL-6 is a cytokine produced by various immune cells in response to infection and tissue injury, promoting inflammation and stimulating immune responses." (PMID 39162542, 2024). "We also detected lower TNF and IL-6 release after infection with R77Q vs. WT." (PMID 39459974, 2024).
infection (continued). "Ferritin, an ARP, is increased in many inflammatory states, and it may serve as a biomarker for CRS, HLH in hematologic disorders, but when used as a predictor of infection, ferritin is affected by a variety of factors including IL-6, IL-10, IL-18, and IFNγ." (PMID 39559703, 2024). "This cytokine, together with IL-6, increases iNOS activation in macrophages, in addition to increasing the expression of chemokines to induce migration of other immune cells to the site of infection, in synergy with IFN-γ." (PMID 39452741, 2024). "Cytokines released by infection, such as IL-1, TNFα and IL-6, will activate the HPA axis, and the endogenous cortisol level in those with preserved adrenal function will increase significantly at this time to inhibit inflammatory cytokines and reduce inflammatory response." (PMID 39741879, 2024). "Furthermore, infection of the CNS increases IL-6 levels, primarily as a response by astrocytes and microglia, potentially reducing the integrity of the BBB and promoting further viral invasion into the CNS37,38." (PMID 38548777, 2024). "Growing evidence indicates that CRP plays a significant role in inflammation and the host response to infection, including the complement pathway, apoptosis, phagocytosis, nitric oxide release, and the release of inflammatory cytokines, particularly interleukin-6 and tumor necrosis factor-alpha." (PMID 39610974, 2024). "However, this treatment was also associated with bacterial superinfections, probably because, while IL-6 is important in host immune defenses, its down-regulation affects the capacity of the body to fight against infections." (PMID 38541700, 2024). "This aspect was also supported by the rapid increase of IL-6 in the first hours of the infection." (PMID 39208074, 2024). "In accordance with this, the expression of cytokines CXCL1, IL-36γ, IL-1β, and IL-6, which are thought to be critical in the recruitment of neutrophils to the infection sites and promoting inflammation, were significantly reduced in the CDI + T.mu group compared to the CDI group." (PMID 38565558, 2024). "H. pylori OMVs activate Toll-like receptor (TLR) signaling pathways, resulting in the release of pro-inflammatory cytokines such as interleukin-1β (IL-1β), tumor necrosis factor-alpha (TNF-α), and interleukin-6 (IL-6), which attract immune cells to the infection site." (PMID 39726601, 2024). "Interestingly, we observed a decrease in the levels of TNF-α and IL-6 in MNK1−/− cells after 6 h of infection with 2 MOI Vv." (PMID 38980024, 2024). "CRP is an acute-phase reactant synthesized by the liver in response to inflammatory cytokines (primarily interleukin 6) generated by white blood cells reacting to microbial pyrogens, with a cut-off between 0.5 and 1 mg/dL in most studies about late-onset infections." (PMID 38535886, 2024). "CRP lacks optimal sensitivity and specificity, IL-6 lacks specificity for hematological malignancies despite its rapid post-infection rise, and PCT may be influenced by coexisting conditions like tumors and thyroid diseases." (PMID 38956649, 2024). "In addition, the percentage change in IL‐6 shows promising application prospects to predict anti‐infection efficacy within 12 h of antibiotic therapy." (PMID 38967137, 2024). "At 6 and 12 h post-infection, a significant increase in IL-6 was observed in RAW 264.7 infected with RB51 and in the LPS-stimulated group, whereas infection with S2308 or stimulation with HKBA did not induce significant changes in IL-6 production during the times evaluated." (PMID 38464511, 2024). "For instance, it appears that these cytocines as proinflammatory factors should increase during infection; IL‐6 and IL‐17A follow this rule, but IL‐F exhibits decreasing results in the study of the plasma concentration of secreted cytokines in toxoplasma patients." (PMID 38270309, 2024). "The RA-YM Δomp71 infection group showed slightly higher levels of IL-6 and IL-8 than the PBS group." (PMID 39407352, 2024).
infection (continued). "Similar to the protein level, the administration of a high dose of GUANKE reduced the transcription of CCL2 (the gene encoding MCP-1), TNFA, and IL6 on the third day after infection, and decreased the transcription of CCL2, TNFA, IL1B, IL6, and IL17C on the fifth day after infection." (PMID 39431894, 2024). "For RSV and IAV coinfection studies in mice, TNF-α and IL-6 were induced during IAV mono-infection." (PMID 38668271, 2024). "Infection with S. uberis induced (p < 0.01) Nrf2, HO-1, IL-6, TNF-α and Atg5." (PMID 38397769, 2024). "IL-6, a 185-amino acid polypeptide, can be detected in the serum during early infection." (PMID 38504206, 2024). "While neutrophils are essential for combating infection, they also contribute to tissue damage and organ dysfunction through the release of reactive oxygen species and pro-inflammatory cytokines such as tumor necrosis factor-alpha and IL-6." (PMID 39553003, 2024). "Next, to explore whether H pylori infection activated DAB2 transcription, we transfected GC cells with DAB2-promoter reporter plasmids and followed by treatment of IL-6 or infection with H pylori." (PMID 38481347, 2024). "For homeostasis, the pro-inflammatory cytokine IL-6 was upregulated during infection." (PMID 38492183, 2024). "We observed higher IL-6 levels in patients with fatal outcomes throughout the infection." (PMID 39408907, 2024). "In the liver, IL-6 is synthesized mainly by KCs upon stimulation of TLRs or tissue injury, providing the induction of acute phase response and hence, early protection against infection." (PMID 38728358, 2024). "The current study also showed a higher host immune cytokine (TNF-α and IL-6) response in the oral cavity and uterus as a result of the polymicrobial infection compared to the CTL, indicating a local and systemic inflammatory response to the microbes and microbial products." (PMID 39203489, 2024). "Additionally, significantly decreased levels of IL-6 correlated with the elimination of infection from the body by day 10 post-infection." (PMID 39204252, 2024). "In contrast, IL-6 levels peaked on day 3 and significantly decreased by day 10 after infection." (PMID 39204252, 2024). "Therefore, we intend to use a larger sample size to further investigate the role of IL-6 in various infections following LGC surgery." (PMID 38504206, 2024). "Moreover, hRSV-infected astrocytes produced IL-4, IL-10, and TNF-α during the first hours of infection and IL-6 in late times." (PMID 39203555, 2024). "Additionally, EV-71 infection in primary monocytes generates an immune response mediated by the secretion of IL-1, IL-6, and TGF-α." (PMID 38248274, 2024). "Furthermore, we compared the values of IL-6 alone and PCT combined with IL-6 in predicting postoperative infection on POD 3 after GC surgery." (PMID 38504206, 2024). "The amplified IL-6 response activates acute-phase proteins, stimulates the development of effector T cells in conjunction with antibody production, forming the link between adaptive and innate immunity, leading to clearance of infection." (PMID 39066403, 2024). "Moreover, IL-6 has been used to predict infectious diseases, such as surgical site infection, nosocomial infection, and post-operative lung infection." (PMID 38504206, 2024). "Interestingly, IL-6 production was detected during infection with MAP strain at any bacterial concentration and at any time point within one week, similarly to uninfected samples." (PMID 38399810, 2024). "In addition, NAg can inhibit interferon-mediated immunity in the first days of infection and the subsequent release of proinflammatory cytokines, including IL-6, IL-1β, and TNF-α." (PMID 38535062, 2024). "In particular, the TNF-α, IL-1β, and IL-6 levels increased by around 18-, 11-, and 13-fold, respectively, at 24 h post-infection and by around 23-, 22-, and 21-fold, respectively, at 48 h post-infection compared to uninfected PAMs." (PMID 38664855, 2024).